CD47 (CD47 molecule)
Diseases named in the same sentence as CD47 in open-access papers (continued):
Sharing a sentence is not in itself a finding about the gene and the disease.
polycythemia (3 papers, 2023 to 2025). Abnormally high mass or concentration of red blood cells in the blood, either due to an increase in erythropoiesis or a decrease in plasma volume. "Smoking has also been identified as a major risk factor for polycythemia as it induces hypoxia and downregulates the levels of CD47." (PMID 40587754, 2025). "Our results show that CD47-SIRPα-signaling in a PV mouse model due to either anti-CD47 treatment or loss of the inhibitory SIRPα-signal corrects the polycythemia phenotype." (PMID 37095207, 2023). "Our results show that blocking CD47-SIRPα in a PV mouse model due to either anti-CD47 treatment or loss of the inhibitory SIRPα-signal corrects the polycythemia phenotype." (PMID 37095207, 2023). "The polycythemia phenotype was restored by intercepting CD47-SIRPα through either anti-CD47 treatment or loss of the inhibitory SIRPα-signal in a PV mouse model." (PMID 38111586, 2023). "Here, we show that blocking the CD47-SIRPα interaction results in the correction of polycythemia in a PV mouse model, which correlates with the expansion of splenic MerTK+ Mdcs and increased phagocytic activity of JAK2 mutant splenic macrophages against RBCs." (PMID 37095207, 2023).
psoriasis (3 papers, 2015 to 2024). An autoimmune condition characterized by red, well-delineated plaques with silvery scales that are usually on the extensor surfaces and scalp. "The random forest algorithm further identified 28 genes significantly associated with psoriasis, including FABP5, CD47, and UBE2F." (PMID 38596682, 2024). "Our results demonstrated a clear and significant reduction in the percentage of IL-17+ cells when these cells were cultured in the presence of TSP-1 or anti-CD47 antibody in psoriasis patients (Friedman test p = 0.003)." (PMID 31214201, 2019). "Expression of TSP-1 and CD47 was analyzed by RT-PCR in skin samples from psoriasis patients and healthy controls." (PMID 31214201, 2019). "Our data showed that peripheral CD4+ T cells from psoriasis patients expressed lower levels of CD47 compared to healthy controls." (PMID 31214201, 2019). "TSP-1 and CD47 expression were analyzed in skin samples from psoriasis patients and control subjects using RT-PCR and immunofluorescence." (PMID 31214201, 2019). "Immunofluorescence staining revealed decreased expression of CD47 in CD45+ dermal cells from psoriasis samples compared to control subjects." (PMID 31214201, 2019). "The functional role of TSP-1/CD47 signaling axis in psoriasis was assessed in Th17 and Treg differentiation assays." (PMID 31214201, 2019). "These assays showed that the anti-CD47 mAb clearly prevented the activation of CD4+ T cells during Ag presentation in cells from psoriasis patients." (PMID 31214201, 2019). "CD47 protein levels were evaluated by flow cytometry in plasmacytoid DCs (pDCs) and myeloid DCs (mDCs) from psoriasis patients and healthy controls." (PMID 31214201, 2019). "Peripheral CD4+ T cells and circulating primary DCs from psoriasis also expressed lower levels of CD47 compared to controls." (PMID 31214201, 2019). "Immunofluorescence assays showed that CD47 is expressed in the dermis and epidermis of both control and psoriasis skin samples." (PMID 31214201, 2019). "Because of the impact of TSP-1/CD47 signaling axis in Th17 and Treg differentiation, a dysregulated expression of these molecules in the immune cells from psoriasis patients may favor the exacerbated inflammatory response in this disease." (PMID 31214201, 2019). "However, both subsets of circulating DCs from psoriasis patients expressed significantly lower levels of CD47 compared to cells from healthy subjects." (PMID 31214201, 2019). "Together these data suggest that TSP-1 and its receptor CD47 may have a role in the exacerbated inflammatory response characteristic of psoriasis." (PMID 31214201, 2019). "Therefore, a diminished expression of TSP-1 and its receptor CD47 in immune cells from psoriasis patients may promote the exacerbated inflammatory response characteristic of this disease." (PMID 31214201, 2019). "To evaluate the functional role of CD47 and TSP-1 in psoriasis inflammatory response we performed Th17 and Treg differentiation assays on peripheral CD4+ T cells from psoriasis patients and healthy controls." (PMID 31214201, 2019). "Similar to our data from psoriasis patients, TSP-1 and anti-CD47 reduced the percentage of IL-17+ cells in cell cultures from healthy donors (Friedman test p = 0.007)." (PMID 31214201, 2019). "Our data demonstrate that TSP-1-CD47 interaction or the incubation with anti-CD47 mAb inhibits the differentiation of Th17 cells and favors CD4+ T cells differentiation into Treg cells from psoriasis patients." (PMID 31214201, 2019). "Similarly, CD47 and UBE2F are involved in aberrant functions of DCs and T cells in various tumors, indicating their potential relevance to psoriasis development." (PMID 38596682, 2024). "Conversely, we did not observe any difference in the levels of CD47 in keratinocytes between psoriasis patients and healthy controls." (PMID 31214201, 2019).
psoriasis (continued). "Quantitative analysis demonstrated diminished levels of CD47 in CD45+ dermal cells of psoriasis patients compared to cells from non-lesional skin or cells from control subjects." (PMID 31214201, 2019). "Our data showed that lesional skin from psoriasis patients express lower levels of TSP-1 and CD47 compared to non-lesional skin or skin from control subjects." (PMID 31214201, 2019). "Lesional skin of psoriasis patients expressed lower TSP-1 and CD47 mRNA levels compared to non-lesional skin or skin from controls." (PMID 31214201, 2019).
renal cell carcinoma (3 papers, 2021 to 2024). "Additionally, CD47 has been identified as a crucial tumor antigen involved in the development and progression of various cancers, including renal cell carcinoma." (PMID 39795582, 2024).
soft tissue sarcoma (3 papers, 2019 to 2024). A malignant neoplasm arising from muscle tissue, adipose tissue, blood vessels, fibrous tissue, or other supportive tissues excluding the bones. "Our objective was to determine CD47 abundance in various soft tissue sarcomas (STS) to investigate whether it could serve as a potential evasion mechanism for tumor cells." (PMID 38493445, 2024).
stomach adenocarcinoma (3 papers, 2023 to 2025). "Moreover, survival analysis conducted using the Kaplan–Meier plotter, which relied on RNA-seq data, further substantiated that elevated CD47 expression in individuals diagnosed with stomach adenocarcinoma generally indicated a diminished likelihood of relapse-free survival." (PMID 38532108, 2024).
actinic keratosis (2 papers, 2022 to 2024). A precancerous lesion of the skin composed of atypical keratinocytes. "They identified that CD47 expression was significantly higher in squamous cell carcinoma in situ (SCCIS) compared to actinic keratosis (AK), and in SCC compared to SCCIS." (PMID 36010209, 2022). "For comparison of CD47 expression, actinic keratosis (AK), squamous cell carcinoma in situ (SCCIS), keratoacanthoma (KA), and normal skin (NS) tissue were used." (PMID 36010209, 2022).
allergic asthma (2 papers, 2022 to 2024). A asthma with a basis in a pathological type I hypersensitivity reaction. "Here, we provide a proof of concept that engagement of SIRPα via its ligand CD47 inhibits ILC2 activation and holds promise for therapeutic intervention in allergic asthma." (PMID 39160226, 2024).
aneurysm (2 papers, 2024 to 2025). Bulging or ballooning in an area of an artery secondary to arterial wall weakening. "Furthermore, the temporal dynamics of CD47 expression during aneurysm development remain undefined, as do the pharmacokinetics and vascular safety of anti-CD47 agents in chronic, non-malignant inflammatory settings." (PMID 41303525, 2025). "Proefferocytic anti-CD47 antibody therapy promotes TGF-β signaling and prevents aneurysm formation." (PMID 38916960, 2024).
asthma (2 papers, 2022 to 2024). "Additionally, we examined the expression of Sirpα and Cd47 in immune cells, including ILC2s, within the intestinal tract and abdominal cavity of a mouse model of inflammatory bowel disease using public databases, and the results were comparable to the mouse asthma model." (PMID 39160226, 2024). "We analyzed the expression of Sirpα and Cd47 in Th1, Th2, Th17, ILC1, ILC2, and ILC3 cells using publicly available scRNAseq data generated from a mouse asthma model." (PMID 39160226, 2024). "Our experiments using genetically modified mice showed that the absence of either SIRPα or CD47 leads to increased ILC2 function, development AHR and lung inflammation in both acute and chronic models of asthma." (PMID 39160226, 2024).
autoimmune uveitis (2 papers, 2015 to 2021). An autoimmune form of uveitis (disease). "In summary, our data demonstrate that systemic CD47 deficiency is protective for autoimmune uveitis." (PMID 34093583, 2021). "Our current study demonstrates how CD47 depletion is effective in the prevention of experimental autoimmune uveitis (EAU), an animal model of human autoimmune uveitis, in animals deficient of CD47 (CD47-/-)." (PMID 34093583, 2021). "To evaluate the overall contribution of CD47 in development of autoimmune uveitis, we assessed disease severity in mice with a systemic deficiency of CD47." (PMID 34093583, 2021). "Here we demonstrate that systemic expression of CD47 is essential in induction of autoimmune uveitis through promotion of development of SIRPα+ DCs which has a crucial role in the priming of autoreactive CD4+ T cells." (PMID 34093583, 2021). "Overall our results demonstrated that CD47 plays an important role in development of autoimmune uveitis by promoting SIRPα+ DC maturation." (PMID 34093583, 2021). "Since CD47 interacts with multiple receptors and are involved in complex mechanism of immune regulation, various CD47 receptors could be a treatment option for autoimmune uveitis." (PMID 34093583, 2021). "Thus, further investigation is needed to elucidate the function of CD47 and its receptors and find a possible treatment option in autoimmune uveitis." (PMID 34093583, 2021). "Our results demonstrated that a systemic loss of CD47 is protective in autoimmune uveitis, whereas local retinal loss of CD47 does not affect disease severity." (PMID 34093583, 2021). "In this study, we examined the role of CD47 in development of autoimmune uveitis." (PMID 34093583, 2021).
B-cell acute lymphoblastic leukemia (2 papers, 2024). A neoplasm of lymphoblasts committed to the B-cell lineage, typically composed of small to medium-sized blast cells. "CD47 promotes cell adhesion by interacting with SIRPα which has been elucidated using an extracellular SIRPα-human Ig fusion protein to promote the CD47-mediated adhesion of B-cell acute lymphoblastic leukemia cells by inducing PI3K activation." (PMID 39039207, 2024).
bladder urothelial carcinoma (2 papers, 2023 to 2025). "Also, the substitution of Asn206 by Ser in leukocyte surface antigen CD47 was identified as a somatic mutation in bladder urothelial carcinoma (COSMIC database)." (PMID 39796186, 2025). "A CD47 antibody (anti-CD47) has been utilized in targeted imaging and tumor-specific administration for bladder urothelial carcinoma." (PMID 36937442, 2023).
brain infarct (2 papers, 2021 to 2024). "Research utilizing CD47 knockout mice indicates that deletion of CD47 reduces brain infarction and edema during the acute phase in the middle cerebral artery occlusion (MCAO) model by mitigating neuroinflammation." (PMID 39660125, 2024). "In ischemic stroke, a study using CD47 knockout mice suggests that CD47 deletion reduces brain infarct and swelling at an acute stage in MCAO model through decreasing neuroinflammation." (PMID 35082781, 2021).
brain injuries (2 papers, 2021 to 2022). "Moreover, CD47 has broad involvement in the death of neuronal cells, neuroinflammation, and the progression of acute ischemic brain injuries." (PMID 34203368, 2021).
Canavan disease (2 papers, 2025). A neurodegenerative disorder; its spectrum varies between severe forms with leukodystrophy, macrocephaly and severe developmental delay, and a very rare mild/juvenile form characterized by mild developmental delay. "For instance, OPCs derived from B2M/CIITA KO iPSCs were shown to express high levels of CD47, a “do-not-eat-me” signal that inhibits phagocytosis by monocytes and macrophages, potentially facilitating their integration into the demyelinating brain of the Canavan disease." (PMID 40655027, 2025).
candida infection (2 papers, 2015 to 2018). "We propose that CD47 is required in the host to mount a balanced protective immune response against candidiasis." (PMID 26010544, 2015). "However, unique to the lower FRT mucosa, epithelial CD44 and CD47 expression was independent on the candida infection, because neutrophil infiltration and functions must be timed to the ovarian cycle." (PMID 29881378, 2018). "cd47-/- mice exhibit poorly controlled pro-inflammatory responses to Candida infection." (PMID 26010544, 2015).
Candidemia (2 papers, 2015 to 2016). A form of invasive candidiasis where species of CANDIDA are present in the blood. "Our data suggests that a defective adaptive immune response also contributes to the increased susceptibility of cd47-/- mice to candidemia." (PMID 26010544, 2015). "Thus, regulation of early humoral immunity is not a major function of CD47 in candidemia." (PMID 26010544, 2015).
cardiac hypertrophy (2 papers, 2017 to 2019). "The TSP1/CD47 mechanism is implicated in CaKMII-mediated cardiac hypertrophy." (PMID 28714932, 2017).
chronic kidney disease (2 papers, 2020 to 2026). Impairment of the renal function secondary to chronic kidney damage persisting for three or more months. "However, it is also important to demonstrate the potential efficacy of CD47 blockade in the prevention of progression of AKI to chronic kidney disease (CKD) and prove that αCD47Ab does not merely delay the onset of AKI." (PMID 32332767, 2020).
crescentic glomerulonephritis (2 papers, 2023 to 2025). A histopathologic term for a pattern of diseases characterized by extensive crescent formation in the glomeruli; patients present clinically with rapid deterioration of renal function, and possible progression to end-stage renal failure within weeks or months. "We investigated the involvement of CD47 in crescentic glomerulonephritis using human renal tissues from patients with AAV and performed a series of in vitro experiments to examine the effects of CD47 blockade on the efferocytosis of NETs." (PMID 37368493, 2023). "The blockade of CD47 in spontaneous crescentic glomerulonephritis-forming/Kinjoh (SCG/Kj) mice ameliorated renal disease and reduced myeloperoxidase-ANCA (MPO-ANCA) titers with a reduction in NET formation." (PMID 37368493, 2023). "Blockade of CD47 improves renal involvement in spontaneous crescentic glomerulonephritis-forming/Kinjoh (SCG/Kj) mice via the restored efferocytosis of NETs." (PMID 37368493, 2023). "Enhanced expression of CD47 in crescentic glomerulonephritis of patients with AAV." (PMID 37368493, 2023). "Similarly, CD47 blockade has been found to reduce NET release and ameliorate renal injury in a mouse model of crescentic glomerulonephritis." (PMID 40338657, 2025).
cutaneous squamous cell carcinoma (2 papers, 2021 to 2024). "The SCC‐13 cutaneous squamous cell carcinoma cell line and HepG2 hepatoma cell line exhibited high CD47 expression." (PMID 33629544, 2021).
demyelinating disease (2 papers, 2021 to 2024). A broad group of disorders that affect the myelin sheaths that cover the neurons. "Our results identify potential detrimental side effects on the CNS by treatments using CD47-blocking Ab that should be considered when treating patients with demyelinating disease." (PMID 34591795, 2021). "Our results have wider implications beyond the EAE model and identify potential detrimental side effects on the CNS of treatments using CD47-blocking Ab that should be considered when treating patients with demyelinating diseases." (PMID 34591795, 2021).
fibrosarcoma (2 papers, 2020 to 2022). A malignant mesenchymal fibroblastic neoplasm affecting the soft tissue and bone. "Furthermore, CD47 was shown to enhance the recruitment of CD8+ T cells in a fibrosarcoma model suggesting a complex regulatory function of CD47 in the TME." (PMID 36171566, 2022).
fibrosis (2 papers, 2020). the formation of excess fibrous connective tissue in an organ or tissue in a reparative or reactive process. "Using an in vivo mouse model of fibrosis, we found two distinct mechanisms by which blocking IL-6, CD47 and PD-L1 reversed fibrosis, by increasing phagocytosis of profibrotic fibroblasts and by eliminating suppressive effects on adaptive immunity." (PMID 32493933, 2020).
graft versus host disease (2 papers, 2022 to 2025). An immune system disorder that occurs after allogeneic hematopoietic stem cell transplant and is a reaction of donor immune cells against host tissues. "Although ILCs lack TCRs and do not cause graft-versus-host disease, allogeneic CAR-ILCs may still trigger host immune rejection, necessitating immune-evasive strategies such as HLA class I knockout or CD47 overexpression." (PMID 40963622, 2025).
gynecologic cancers (2 papers, 2023). "The objective was to correlate CD47 gene expression with resistance to immune checkpoint inhibitors (ICI) in tumor tissue of gynecological cancer (GC)." (PMID 37468567, 2023). "Although magrolimab has been approved for the treatment of hematopoietic malignancies and several other CD47/SIRPα inhibitors have been assessed in many advanced cancers, clinical data about the efficacy of CD47/SIRPα inhibitors in patients with gynecological cancers are rare." (PMID 37368179, 2023).
kidney cancer (2 papers, 2021 to 2024). Primary or metastatic malignant neoplasm involving the kidney. "Similarly, over 48% of patients in all indications except kidney cancer (35%) had high CD47 expression." (PMID 39627379, 2024). "When considering patients that were high for both CD36 and CD47, 11 out of 13 indications had more than 47% of cases with dual high levels of CD36/CD47, with Kidney Cancer (37%) and HCC (35%) as the exception." (PMID 39627379, 2024). "Finally, some indications, such as Kidney cancer and Melanoma, had no distinct pattern of CD36/CD47 expression levels across different disease stages." (PMID 39627379, 2024).
kidney injury (2 papers, 2020 to 2025). Trauma to the kidney. "NEX is injected into the CI-AKI mouse model and can effectively act on the site of kidney injury; enhance antioxidant stress, anti-inflammatory, and anti-apoptotic; and the expression of CD47+ on NEX membrane can inhibit the macrophage absorption of them." (PMID 40332144, 2025).
lupus nephritis (2 papers, 2021 to 2023). Glomerulonephritis in the context of systemic lupus erythematosus. "Lastly, we investigated whether CD47 expressing cells were present in the kidney of eight patients with lupus nephritis (LN)." (PMID 34068752, 2021). "Finally, CD47+ CD68+ macrophages were present in lupus nephritis." (PMID 34068752, 2021). "To assess the expression of CD47 in the kidney, we first performed IHC staining for CD47 in human renal biopsy specimens from patients active AAV and other control diseases including lupus nephritis (LN) class IV, LN class V, and minor glomerular abnormalities (MGA) as a control." (PMID 37368493, 2023).